LRP5L (LDL receptor related protein 5 like (pseudogene))
Synonyms: DKFZp434O0213
Gene: Transcribed unprocessed pseudogene on chromosome 22 (25,351,612 to 25,405,274, reverse strand). Ensembl gene ENSG00000100068.
Diseases named in the same sentence as LRP5L in open-access papers:
LRP5L is named in the same sentence as 2 diseases in open-access papers, as found by Europe PMC text mining. Sharing a sentence is not in itself a finding about the gene and the disease. The quoted sentences say what the papers report.
tumor (2 papers, 2021 to 2023). "LDL Receptor Related Protein 5 Like (LRP5L) is a key gene involved in the regulation of Wnt signaling pathway, which plays an important role in tumor progression." (PMID 37483484, 2023).
cancer (1 paper, 2023). A tumor composed of atypical neoplastic, often pleomorphic cells that invade other tissues. "In the single variant cross-cancer meta-analysis, the most significant SNP rs78345670 resides in the intronic region of LRP5L, which is also one of the most significant genes in SKAT-O analysis shared by all three cancers." (PMID 37483484, 2023). "Taken together, EXOC6/rs1339820 and ABCC11/rs75797074 showed some cross-cancer susceptibility in CG and CRC, and LRP5L maybe a potential susceptibility gene in GI cancers." (PMID 37483484, 2023). "Among which three genes, EXOC6 (Padj|ESCC=7.30×10-3, Padj|GC=6.00×10-4, Padj|CRC=2.6×10-2), LRP5L (Padj|ESCC=2.70×10-3, Padj|GC=5.70×10-3, Padj|CRC=1.65×10-2), MIR1263/LINC01324(Padj|ESCC=3.22×10-2, Padj|GC=4.36×10-2, Padj|CRC=3.26×10-2) were statistically significant in all three cancer types." (PMID 37483484, 2023).